CD68 (CD68 molecule)
Diseases named in the same sentence as CD68 in open-access papers (continued):
Sharing a sentence is not in itself a finding about the gene and the disease.
COVID-19 (79 papers, 2020 to 2026). A disease caused by infection with severe acute respiratory syndrome coronavirus 2. "Since CD4 and CD68 are usually present on the macrophage surface, macrophages appear to be the driving force of COVID-19-associated inflammation, especially if trophoblast necrosis is present." (PMID 39057113, 2024). "In COVID-19 patients, abnormal activation of macrophages expressing M1/M2 polarization markers (CD68, CD80, CD163, and CD206) in the lung is associated with the production of cytokines, including IL-6, IL-10, and TNF-α, as indicated by previous studies." (PMID 39100091, 2024). "Our data showed an increased pan-macrophage marker CD68 in COVID-19(+) patients associated with imbalance of M2-like sub-populations." (PMID 37686069, 2023). "The strong positive correlation between microglial density and CD68 immunoreactive area further underlines the activated phenotype displayed by microglial cells in COVID-19." (PMID 36781876, 2023). "Similar to COVID-19, infection with mCoV-A59 caused increased cardiac inflammation in old mice as evaluated by greater number of infiltrating CD68+ myeloid cells." (PMID 34151773, 2021). "In addition, histopathology with immunohistochemistry was able to confirm the presence of CD68+ macrophages, which have been associated with damage to other organs in cases of moderate to severe COVID-19." (PMID 37297922, 2023). "In the vast majority of cases, we detected lymphocytic myocarditis with variable numbers of macrophages (CD68+, more often in post-COVID-19 myocarditis)." (PMID 39858598, 2025). "Despite the high basal level of FTL in macrophages, we found FTL signals outside of macrophage markers (CD68 and CD11c) in severe COVID-19 lungs, suggesting that other alveolar cell types were involved in FTL upregulation." (PMID 38769293, 2024). "Several studies have demonstrated that patients with severe COVID-19 have increased inflammatory monocyte and CD68+ macrophage infiltration and a corresponding decrease in anti-inflammatory alveolar macrophages." (PMID 39100091, 2024). "Compared to healthy controls, individuals with post-COVID-19 revealed a high percentage of TMEM119+P2RY12+CD68+Iba1+HLA-DR+CD11c+SCAMP2+ microglia assembled in prototypical cellular nodules." (PMID 39060438, 2024). "The expression of CD68+ was elevated in the COVID-19 cohort, suggesting that macrophages constituted a significant part of the inflammatory infiltrate." (PMID 39057113, 2024). "Immune cells, especially CD68+ macrophages, were more abundant in the NP+ group than in the NP− group, suggesting a potential crucial role for these cells in COVID-19-related inflammation and GI symptoms." (PMID 39100091, 2024). "For example, microglia cells in cluster 1 exhibited strong positivity for the lysosomal activation marker CD68 and were mostly observed in samples from acute and post-COVID-19 patients, with minimal representation in control samples." (PMID 39060438, 2024). "CD68-positive clusters were detected in 10 patients (patients 2, 3, 4, 7, 8, 10, 11, 13, 14, 15), representing 59% of analyzed COVID-19 autopsies." (PMID 37521293, 2023). "Pathomorphological studies of the lungs of those patients who died from COVID-19 showed the presence of pneumocytes, CD68+ macrophages, and CD3+ T cells with the activation of STAT6 expression in the inflammatory infiltrates." (PMID 37109672, 2023). "Immunofluorescence staining of the adipose tissue from deceased COVID-19 patients revealed SARS-CoV-2 spike protein colocalization with the macrophage marker CD68." (PMID 37587162, 2023). "CD68-immunoreactive clusters were detected in 10 of 17 COVID-19 patients representing 59% of patients." (PMID 37521293, 2023). "Weckbach and colleagues found in five patients with COVID-19 and myocarditis a prevalent infiltrate of CD68+ macrophages with few CD3+ T cells." (PMID 37112659, 2023).
COVID-19 (continued). "Lymphocytic infiltration with predominant immunostaining for CD8 and CD68-positive cells (macrophages) is present in myocarditis following COVID-19 mRNA vaccines." (PMID 37112659, 2023). "In multiplex immunofluorescence significantly more CD68 positive macrophages were found in the cortex of COVID-19 patients compared to influenza patients (mean number/HPF 27.6 ± 9 versus 16.7 ± 3.7; p < 0.0001)." (PMID 35332140, 2022). "CD68 + macrophages and atypical giant cells have been observed in alveolar spaces in COVID-19 patients, and type II pneumocytes with the enlarged, bright, eosinophilic nucleoli have been reported to increase in size in the diseased condition." (PMID 34463916, 2022). "A comparison of CD3+ T cells and CD68+ macrophages in patients with COVID-19 and control patients was reported in a recent review." (PMID 36312241, 2022). "Still, we observed that the increased expression of ACE2 in COVID-19 thrombi was mainly driven by a subset of CD68+ monocyte/macrophages within the thrombus." (PMID 35105380, 2022). "HC counting revealed an average number of 1,7 CD68+ cell/villous in the COVID-19 group and 1,2 CD68+ cell/villous in the Control group (p=0.12)." (PMID 34122449, 2021). "Using the same dataset of single-cell transcriptomes of bronchoalveolar cells in patients with mild and severe COVID-19, we decided to examine the relationship between CD68+ macrophages and immunoproteasome components in more detail." (PMID 34225749, 2021). "The results showed that in the lung tissues of patients with COVID-19, CyPA had strong positive correlations with CD68, CCL2, and IL-6." (PMID 34564690, 2021). "With the R-package monocle, we constructed a cell trajectory of PSMB8 expression in the CD14+/CD68+ subpopulation of bronchoalveolar cells from COVID-19 patients." (PMID 34225749, 2021). "Prior data in COVID-19 have shown that accumulation of CD68+ macrophages and activated cytotoxic CD8+ T cells are positively associated with diffuse alveolar damage." (PMID 34835015, 2021). "In this study, we showed that enriched populations of Res-like Mac (HLA-DR+ITGAM−CD68low), M1 Mac (CD68+ITGAM+CCL2+), and pro-inflammatory Mac (CD68+ITGAM−CSF1R−CCL2+) in patients with severe COVID-19." (PMID 34238338, 2021). "Perivascular activated (CD68-positive) microglia in the brainstem have previously been reported as a common finding in COVID-19 patients." (PMID 34949230, 2021). "The prominent M2 Mac (C1QA+CCL18+), and M0 Mac (CD68+CD163lowITGAM+) were enriched in normal controls compared to COVID-19 patients." (PMID 34238338, 2021). "SPP1 and CD68 staining of postmortem lung tissue confirmed abundant clusters of SPP1+ macrophages in alveoli of COVID-19 patients (n = 2), while it was rare in normal lung (n = 3) and sparse in alveoli of bacterial (n = 3) and H1N1 (n = 3) pneumonia." (PMID 34143756, 2021). "This study revealed an abundant number of CD68+ macrophages in the hearts of patients who died of COVID-19." (PMID 34573988, 2021). "Recent evidence showed massive macrophage infiltration of the lungs of deceased COVID-19 patients, including intra-alveolar CD68+ macrophages." (PMID 34603560, 2021). "First, we found that monocytes (CD14 and CD68) infiltrated the lungs and intestines of patients with COVID-19." (PMID 33424804, 2020). "However, we identified COVID-19-associated syncytial macrophages with high phagocytic activity in the lung that were positive for NRP1 and CD68 by CODEX and IHC." (PMID 41159753, 2025). "Similarly, postmortem analyses of COVID-19 patients have revealed increased numbers of CD68+ macrophages in the lungs, and their activation has been implicated in pulmonary tissue damage." (PMID 40822581, 2025). "Post-mortem testes of COVID-19 individuals showed increased number of CD68 macrophages." (PMID 40496014, 2025). "Post-COVID-19 placentas showed few CD68 positive macrophages in male and female deciduas." (PMID 39589546, 2024).
COVID-19 (continued). "Similarly, in the neural tissues of patients with severe COVID-19, the presence of CD68+ activated microglia and CD8+ cytotoxic T lymphocytes exacerbates the severity of neuroinflammation." (PMID 39100091, 2024). "The expression levels of CD4+, a T cell marker, and CD68+, a macrophage marker, were significantly higher in the COVID-19 group than in control samples, suggesting that T lymphocytes and macrophages drive the pathological changes associated with SARS-CoV-2 infection." (PMID 39057113, 2024). "Histopathological examination of GI tissues from COVID-19 patients revealed pronounced acute responses, especially in duodenal tissues, characterized by the predominant presence of inflammatory cells, specifically CD68+ macrophages and CD3+CD4+ T-cells." (PMID 39100091, 2024). "Correlations between CD68+ macrophages and clinicopathological features in patients with COVID-19." (PMID 39100091, 2024). "Therefore, WGCNA of GI tissues from COVID-19 patients further highlighted the potential crucial role of CD68+ macrophages in the abnormal GI function observed in COVID-19 patients." (PMID 39100091, 2024). "Hence, evaluating the immunoexpression of CD68 results, it is observed that it was significantly increased in the COVID-19 group (p = 0.013)." (PMID 36430210, 2022). "In addition, we found diffuse myocardial CD68+ cell infiltration in the patient biopsy sample, suggesting an increased level of IL-18 produced by monocytes and macrophages in the heart with COVID-19 vaccine-related myopericarditis." (PMID 35251049, 2022). "We observe an abundance of CD68-positive cells in ChP of COVID-19 cases, and these cells do not appear to be associated with a blood vessel." (PMID 34281603, 2021). "In mild cases of COVID-19, we further observed that the expression of PSMB8 in alveolar monocytes/macrophages was correlated with that of genes associated with the polarization of M1 macrophages, such as CD68, MYD88, and STAT1." (PMID 34225749, 2021). "The authors suggested that the CD68-positive infiltrate revealed by COVID-19 patient postmortem analysis might explain the circulating loss of these cell populations, with basophils involved in tissue repair and regulation of the coagulation process." (PMID 34685733, 2021). "The lung parenchyma of patients with COVID-19 might contain inflammatory components characterized by numerous CD68-positive macrophages and only a few CD45 lymphocytes that are found primarily in the interstitial space." (PMID 33394313, 2021). "The predominant changes in the hilar lymph nodes were mildly to moderately expanded subcapsular sinuses infiltrated with CD68-positive macrophages in COVID-19 cases in comparison with the control lung carcinoma cases without tumor metastasis into hilar lymph nodes." (PMID 34676085, 2020). "However, consistent and diffuse expression of pSTAT3 was shared in COVID-19 samples by numerous cell types; among them, several CD68+FLIP+ alveolar macrophages (third and fourth lines), histiocytic cells (fifth and sixth lines), and monocytes/interstitial macrophages." (PMID 34518653, 2022). "Likewise, the expansion of inflammatory-oriented microglial clusters marked by increased intensity of IBA1, HLA-DR, and CD68 immunoreactivity and increased density of microglial nodules found in post-mortem brains of COVID-19 patients would be in line with this ongoing microgliosis." (PMID 33737867, 2021). "Post-COVID-19 patients showed higher counts of CD3+ lymphocytes (p = 0.02) and lower counts of CD68+ macrophages (p = 0.04), as well as more frequent and extensive regenerative changes in hepatocytes and the biliary epithelium (p = 0.0007)." (PMID 41600833, 2026). "An increase in CD3+, CD4+, CD68+, CD163+, and CD20+ CD138+ immunocompetent cells was found in the appendix of children with COVID-19." (PMID 38397914, 2024).
COVID-19 (continued). "The levels of COVID-19 microenvironment markers, i.e., CD3, CD4, CD8, CD20, CD68, vimentin, NP, ACE2, Granzyme B, E-cadherin, and phosphorylated nuclear factor kappa B (p-NFκB), were measured via IMC." (PMID 39100091, 2024). "A significant expression of vimentin and infiltration of immune cells (CD68+, CD38+, and CD138+) in the testicular tissue of COVID-19 cases, along with extensive immunoglobulin G precipitation and reduced inhibin expression (p = 0.001) were observed." (PMID 39866583, 2024). "Determine the cellular character of the inflammatory infiltrate in children of different age groups with COVID-19 based on the levels of expression of immunocompetent cell differentiation clusters: CD3, CD4, CD20, CD68, CD163, and CD138." (PMID 38397914, 2024). "CD34 expression was lower in the COVID-19 group (p = 0.048), while CD4, CD68, and vimentin levels were higher in the COVID group (p < 0.05)." (PMID 39057113, 2024). "To gain a deeper understanding of CD68+ macrophages and their interactions with CD4+ and CD8+ cells, we conducted RNA-seq analysis of COVID-19 GI tissues and WGCNA to identify key hub genes." (PMID 39100091, 2024). "In this study, the expression of macrophage markers (CD68 and CD163), ACE2, and caspase-3 was investigated based on the results of two fatal clinical observations of COVID-19." (PMID 37109672, 2023). "In a series of report cases of myocarditis following COVID-19 mRNA vaccination, studied with EMB, there is a mixed inflammatory infiltrate in which CD3 T lymphocytes and macrophages CD68 are always present." (PMID 37112659, 2023). "In comparison to normal/near normal areas within COVID-19-positive case 2, ROIs representing diffuse damage contained a markedly increased expression of CD3, CD4 and CD68, in terms of density per square millimetre." (PMID 36717223, 2023). "Two other cases with acute myocarditis following COVID-19 mRNA vaccination, at EMB analysis, have elevated CD3 T cells and CD68 macrophages." (PMID 37112659, 2023). "Significantly increased tissue immunoexpression of Arginase, CD4, CD68, CD138, Perforin, Sphingosine-1, and IL-4 markers were observed in the COVID-19 group." (PMID 36430210, 2022). "The R848-treated myeloid populations from COVID-19 patients also showed reduced expression of HLA-DR and enhanced expression of CD38, CD68, CD80, and CD206, which was similar to the untreated condition." (PMID 36085197, 2022). "Surrounding the brain vasculature in COVID-19 patients, we detected CD4+ and CD8+ T cells, as well as CD68+ macrophages, indicative of perivascular inflammation, rather than widespread neuroinflammation in the brain parenchyma." (PMID 34769052, 2021). "Then we detected the expression of CyPA, macrophage marker CD68, CCL2, and IL-6 in lung tissues from 13 cases of COVID-19 patients using multiplex immunofluorescence." (PMID 34564690, 2021). "In addition, immunohistochemical staining revealed severe infiltration of CD68+ (macrophages), CD38+ (activated B cells), and CD138+ (plasma cells) in the interstitial compartments of testis tissue of the COVID-19 group." (PMID 39866583, 2024). "Our study showed a significant overexpression of pan-macrophage marker CD68 in lungs of deceased COVID-19 cases as compared to SARS-CoV-2 negative control lungs." (PMID 37686069, 2023). "Patients who died from COVID-19 showed a significant increase in CD4, CD68, and CD138." (PMID 37109672, 2023). "In investigating whether our findings could be extended to severe COVID-19 patients, tissue microarray analysis showed that SARS-CoV-2-induced pneumonia from post-mortem patients coincided with significant infiltration of CD68+ macrophages." (PMID 35512020, 2022). "Consistent with COVID-19 CRS, we detected pSTAT3 in both mononuclear phagocytes (hereafter identified as either CD68+, F4/80+ or Ly6C+ cells) and neutrophils (hereafter identified as either NE+ cells or Ly6G+ cells) localized in vFLIP lung tissues compared to normal mice." (PMID 34518653, 2022).
COVID-19 (continued). "In addition to clinical biomarkers data and echocardiographic studies, published reports of COVID-19 cases seldom report positive CD3+ lymphocyte and CD68+ macrophage cell numbers or only report as cells positive per field of view." (PMID 35203260, 2022). "Although we did see increased CD68 levels in the COVID-19 lungs, we did not see evidence of p4EBP1 staining in CD68 positive cells, suggesting that the cells with mTORC1 activation in the COVID-19 patient lung biopsies are not macrophages." (PMID 33767183, 2021). "Specifically, along with CD68, the immunoproteasome-related genes PSMB8, TAP1, PSMB9, PSMB10, and calreticulin (CALR) were all found to be expressed in the CD14+/CD16+ subpopulation of cells during mild COVID-19." (PMID 34225749, 2021). "Similarly, in the trajectory signature for alveolar macrophages from mild COVID-19 patients, CALR, MARCO and TNFSF13 followed the expression patterns of CD68 and PSMB8." (PMID 34225749, 2021). "Immunohistochemical experiments were performed only in COVID-19 lung parenchyma for CD61 (megakaryocyte marker), CD68 (histiocytic marker), and Ki67 (proliferation index) to better characterize the cells with abnormal and irregular nuclei present in the lung interstitium." (PMID 34831356, 2021). "COVID-19 group demonstrated significantly increased tissue immunoexpression of Arginase-1 and IL-4 (p = 0.002 and p < 0.0001, respectively) and increased number of Perforin-1+ (p = 0.009), CD4+ (p = 0.009), CD68+ (p = 0.013), CD138+ (p < 0.0001) cells in comparison to the H1N1 group." (PMID 36430210, 2022). "Immunohistochemical examination of the vermiform appendages in children with confirmed COVID-19 revealed a predominance of CD3+, CD4+, CD20+, CD138+, CD 163+, and CD68+ cells compared to acute appendicitis without COVID-19 infection and the control group." (PMID 38397914, 2024). "In COVID-19-related AIDP, one small histological series demonstrated no viral invasion but primarily CD68+++ histiocytes, often accompanied by cytotoxic CD8++ T-cells and less frequently helper CD4+ T cells." (PMID 37712090, 2023). "Compared to controls and to COVID-19 specimens that were negative for virus in WAT, virus-positive specimens showed significantly increased numbers of cells expressing CD45 pan-leukocyte marker (p < 0.01), CD3 T-cells (p < 0.05), CD57 natural killer cells (p < 0.05), and CD68 macrophages (p < 0.05)." (PMID 35169984, 2022).